DDR2 (discoidin domain receptor tyrosine kinase 2)
Diseases named in the same sentence as DDR2 in open-access papers (continued):
Sharing a sentence is not in itself a finding about the gene and the disease.
tumor (continued). "Thus, both +DDR1b and +DDR2 tumours in COL1 share a common and significant downregulation of MST2." (PMID 32047176, 2020). "Therefore, collagen aging promotes tumor cell proliferation by reducing the activation of DDR2." (PMID 31379950, 2019). "UC tumor cells may take advantage of DDR2 to enhance proliferation via EMT." (PMID 27793038, 2016). "The mechanism by which DDR2 and its mutations may contribute to oncogenesis in lung SCC is not well known; however, given its role in transmitting signals from the ECM, it is likely that DDR2 could act as regulators of cell proliferation, migration and subsequent tumor cells metastasis." (PMID 24885564, 2014). "In patients with the DDR2 mutations, corresponding primary tumor was not available." (PMID 25173530, 2014). "DDR1 and DDR2 are pivotal in bridging cancer cells with ECM, driving tumor progression through diverse mechanisms." (PMID 40563472, 2025). "Dual inhibition impaired DDR2 and KRAS activity and induced robust apoptotic responses through mitochondrial pathways, leading to significant tumor growth inhibition in vivo." (PMID 39941857, 2025). "Upon activation, DDR1 and DDR2 regulate cell proliferation, differentiation, and ECM responses, contributing to tumor progression through altered gene expression." (PMID 40721833, 2025). "In invasive ductal carcinoma (IDC), type I collagen stabilizes the EMT transcription factor Snail via the DDR2-ERK signaling axis, facilitating tumor metastasis." (PMID 40563472, 2025). "Violin plot analysis of the various cell clusters present revealed that DDR2 was expressed in the three PDGFRΑ+ CAF clusters and one tumor cell subpopulation." (PMID 37996700, 2024). "Arg1 mRNA expression was present in two of the three Ddr2+ CAF clusters as well as in two immune cell clusters and one tumor cell cluster." (PMID 37996700, 2024). "To clarify the specific role of fibroblast DDR2 in tumor progression, we performed the omental colonization assay and determined that CAF DDR2 and arginase affects the early steps of tumor progression." (PMID 37996700, 2024). "In all three experimental settings, ubiquitous Ddr2−/− recipient mice developed significantly less tumor burden than the WT mice, and the ID8TB−/− model in DDR2 KO mice had increased survival and decreased ascites compared to the DDR2 WT mice." (PMID 37996700, 2024). "The proportion of Arg1-positive macrophages (%Arg1+ and F4-80+/ F4-80+) and Arg1-positive tumor cells (%Arg1 and CK8+/CK8+) were similar between tumors from WT and Ddr2−/− mice." (PMID 37996700, 2024). "For the Matrigel transwell invasion assay, we used conditioned media from DDR2-expressing, DDR2-depleted, and DDR2-depleted + POSTN-overexpressing CAFs as chemoattractant for tumor cell invasion." (PMID 35884543, 2022). "Using Chi-square and Fisher's exact test, we found a strong correlation between intratumoral DDR2 protein levels and CAFs infiltration (characterized by α-SMA expression) in breast IDC samples." (PMID 35711892, 2022). "We aimed to identify if DDR2 expression in tumor cells regulates POSTN expression, so we performed immunoblotting on a panel of DDR2-expressing and DDR2-depleted cells." (PMID 35884543, 2022). "Since collagen 1 is a ligand of DDR2, we also studied the effect of DDR2′s modulation of POSTN on tumor cell migration through a 3D collagen extracellular matrix (ECM)." (PMID 35884543, 2022). "We found that mesothelial cell clearance and invasion by tumor cells were enhanced three-fold when DDR2 and POSTN-expressing CAFs were present compared to DDR2 and POSTN-depleted CAFs." (PMID 35884543, 2022). "Compared with the cholesterogenic subgroup, the glycolytic subgroup had higher rates of DDR2 and TPR CNV and higher proliferation scores and MK167 expression levels, but a lower tumor purity proportion." (PMID 34384498, 2021).
tumor (continued). "Taken together, these CAF paracrine experiments indicated that DDR2 signaling in CAFs was critical for CAF paracrine regulation of single and collective tumor cell migration through 3D collagen I matrices." (PMID 34477203, 2021). "Treatment with the anti-tyrosine kinase inhibitor dasatinib (anti-DDR2) and anti-PD-1 resulted in increased CD8+ tumor lymphocytes compared to monotherapy and a reduced tumor load." (PMID 33802033, 2021). "In vivo, tumor load reduction and higher CD8+T cells infiltration in tumor were observed in tumor-bearing mice treated by dasatinib (a tyrosine kinase inhibitor of DDR2) plus anti-PD-1." (PMID 34733848, 2021). "Here, we found that +DDR2 tumours showed a consistent and significant downregulation of KIBRA (~140 kDa) when compared to -DDR2 tumours (p = 0.008)." (PMID 32047176, 2020). "First, it will be important to clarify DDR1 and DDR2 respective roles in CRC, specifically in the stromal and tumor compartments." (PMID 32117772, 2020). "Here we report that while both DDR1b and DDR2 significantly restrict HT1080 in vitro cell proliferation in 2D and 3D collagen I matrices, in vivo DDRs accelerate tumour growth only when the cells are implanted within a collagen I (COL1) gel." (PMID 32047176, 2020). "+DDR2/+COL1 tumours also showed higher levels of CYR61 and AXL (1.58 and 1.42 folds, respectively) than −DDR2/+COL1 tumours." (PMID 32047176, 2020). "(D) Primary tumor growth rate in MMTV-PyMT (WT) (n = 18 mice) or FSP1cre; Ddr2fl/fl; MMTV-PyMT (Ddr2-/- FSP1cre) (n = 10 mice) as represented by time in weeks to end stage (single tumor 2 cm in largest dimension)." (PMID 31144616, 2019). "(E) Total primary tumor burden in WT; MMTV-PyMT (WT) (n = 18 mice) or FSP1cre; Ddr2fl/fl; MMTV-PyMT (Ddr2-/- FSP1cre) (n = 10 mice)." (PMID 31144616, 2019). "(F) FACS quantification of percent PDGFRα positive cells (i.e., CAFs) per total primary tumor in size- and age-matched MMTV-PyMT (WT) or FSP1cre; Ddr2fl/fl; MMTV-PyMT (Ddr2-/- FSP1cre) tumors." (PMID 31144616, 2019). "(I) 2D en face rendering of 3D reconstructed FIB-SEM images of tumor-stromal boundary (2–5 μM) from 12 week old MMTV-PyMT (WT), ubiquitous Ddr2-/- null; MMTV-PyMT, or Ddr2-/-; FSP1cre; MMTV-PyMT tumors." (PMID 31144616, 2019). "We have previously shown that HSC-derived DDR2+ cells home to tumor via the CCR2/MCP-1 axis and are capable of differentiating into fibroblasts in the local tumor environment." (PMID 31015794, 2019). "We validated the focal status of gene amplification (size < 10Mb) for 2 tumours (focal amplification of CCND1 for tumour T8 and focal amplifications of DDR2, AKT2 and MDM2 for tumour T16) using array comparative genomic hybridization." (PMID 29416628, 2018). "More than half of the tumor shows infiltrative and trabecular invasion pattern in both UTUC and UBUC groups, significantly corresponding to high DDR2 expression (UTUC and UBUC, P < 0.001)." (PMID 27793038, 2016). "Next, expression of DDR2 and SNAIL1 was assessed by immunohistochemistry in HCC and matched tumor-adjacent tissues." (PMID 26362312, 2015). "Notably, Col1-induced SNAIL1 stabilization occurs independently of integrin and TGFβ, highlighting the unique function of DDR2 in sustaining EMT phenotype and tumor cell invasion through Col1-rich ECM." (PMID 41492134, 2026). "Additionally, we analyzed the DDR2, SHP2 and SRC activity levels in the tumor lysates using Western blotting, observing a significant decrease in protein levels for the dual inhibitor group relative to the untreated group." (PMID 39941857, 2025). "Prior work has shown that DDR2 plays a role in bone development, lipolysis, and ECM deposition in bone and heart, so it is possible that DDR2’s role in other cell types contributes to the observed tumor burden phenotype." (PMID 37996700, 2024). "Moreover, the mouse forestomach tumor from which the MFC cell line was derived had developed spontaneous lung metastasis, making DDR2 a relevant target." (PMID 38554776, 2024).
tumor (continued). "Because some of the DDR2-mediated effects on tumor invasion, migration and metastasis are independent of its kinase activity, targeting DDR2-collagen interaction represents a promising options to halt tumor growth and invasion." (PMID 36249782, 2022). "To determine whether DDR2-expressing CAFs regulated tumor cell invasion, we utilized the DDR2-expressing ES2 tumor cell line." (PMID 35884543, 2022). "Additionally, OmCAFs with high DDR2 and POSTN expression induce tumor cell invasion and in vivo tumor implantation." (PMID 35884543, 2022). "Similarly, the collagen receptor Discoidin Domain Receptor 2 (DDR2) has been used to mark cardiac fibroblasts, but is also found on leukocytes and tumor cells." (PMID 35892569, 2022). "In order to test the effect of DDR2 and POSTN on tumor metastasis, we used DDR2-expressing (CAF shSCRM) and DDR2-depleted CAFs (CAF shDDR2) as well as DDR2-depleted, periostin-overexpressing (CAF shDDR2 POSTN OE), and transfection control (CAF shDDR2 Empty Vector) CAFs." (PMID 35884543, 2022). "We observed a decrease in tumor cell attachment in DDR2-depleted CAF condition compared to DDR2-expressing CAF condition, however these differences were not statistically significant." (PMID 35884543, 2022). "Conditioned medium from both human and mouse parental CAFs increased WT tumor cell invasion through Matrigel, and this activity required the presence of DDR2, as conditioned medium from DDR2-depleted CAFs did not enhance tumor cell invasion." (PMID 34477203, 2021). "Pharmacologic targeting of DDR2 with an allosteric inhibitor such as CR13452, which acts via the extracellular region, blocks all DDR2-dependent cellular effects, including tyrosine kinase-independent effects, in tumor cells and CAFs." (PMID 34477203, 2021). "A study showed that knockdown of DDR2 in the NA13 cell line, B16F10 cell line and mammary tumor cell line E0771 could enhance the sensitivity of tumor cells to anti-PD-1 therapy in vitro." (PMID 34733848, 2021). "In 3D collagen I matrices, tumor cells containing tyrosine kinase domain-truncated DDR2 (ΔKD), as opposed to tyrosine kinase-inactive DDR2 (K608E), were more inhibited in their migratory capacity." (PMID 34477203, 2021). "Collagen I matrices pretreated with CAF-conditioned medium resulted in significantly increased tumor cell migration through 3D collagen I, whereas pretreatment with conditioned medium from DDR2-depleted CAFs did not." (PMID 34477203, 2021). "Following treatment of CAFs with CR13452, conditioned medium from all previously active DDR2-expressing CAFs, including K608E-expressing cells, no longer enhanced tumor cell invasion." (PMID 34477203, 2021). "The ability of collagen to influence immunotherapy could involve DDR2-signaling since treatment of several murine cancer models with a combination of anti-PD-1 antibody and a DDR2-inhibitor led to an increase in CD8+ T cells and a reduced tumor burden." (PMID 34956223, 2021). "DDR2 controls ECM remodeling enzymes' expression, which could lead to enhanced migration and invasion of tumor cells, cleavage of fibronectin, mesothelial cell clearance facilitating metastasis, and decreased survival." (PMID 33859913, 2021). "A switch between DDR1 and DDR2 during tumor progression has been demonstrated, but it is not impossible that a switch between the different DDR1 isoforms during tumor progression may exist." (PMID 33917302, 2021). "The presence and the role of these myeloid-derived CD45+/DDR2+ cells in tumor progression are not known." (PMID 33917302, 2021). "We found that neither DDR1b nor DDR2 overexpression (−DOX diet) had an impact on HT1080 tumour growth rate when compared with tumours with repressed DDR expression (+DOX diet)." (PMID 32047176, 2020).
tumor (continued). "Macroscopic examination of the lungs revealed readily detectable tumour nodules in lungs of mice inoculated with HT-DDR2 cells regardless of DDR2 expression (−DOX and +DOX)." (PMID 32047176, 2020). "In contrast, we found that only +DDR2/+COL1 tumours showed significantly higher levels of pAKT-S473, compared to −DDR2/+COL1 tumours, suggesting that AKT-mediated signalling plays a role in the stimulation of tumour growth in the +DDR2/+COL1 xenografts." (PMID 32047176, 2020). "Quantification of pYAP1 at S127 and S397 revealed that levels of pYAP1-S397 were not altered in both +DDR1b and +DDR2 tumours, when compared to tumours with no DDR induction (third panels from the top, p = 0.401 and 0.343, respectively)." (PMID 32047176, 2020). "Viewed together, these results suggested that the action of DDR2 in the stromal cells within the primary tumor environment, as opposed to the action of DDR2 in stromal cells at lung metastatic site, was important in influencing metastasis." (PMID 31144616, 2019). "But, in which cells within the tumor environment the action of DDR2 is important and how is not known." (PMID 31144616, 2019). "Deletion of Ddr2 with FSP1cre significantly reduced the number of lung metastasis, without affecting primary tumor burden or latency." (PMID 31144616, 2019). "Furthermore, we showed that p300 upregulation on a stiff matrix led to c-Myb acetylation, promoting c-Myb and LEF1 recruitment to the DDR2 promoter and leading to expression of DDR2 and EMT marker genes in the stiff stroma of a developing tumour." (PMID 28754957, 2017). "Thus, DDR2 maintains SNAIL1 protein level and its activity in tumor cells, facilitating cell invasion." (PMID 27014069, 2016). "According to the median ratio of relative DDR2 expression (1.76) in tumor tissues, the 56 NSCLC patients were classified into two groups: High-DDR2 group (n = 27, DDR2 expression ratio ≥ median ratio) and Low-DDR2 group (n = 27, DDR2 expression ratio ≤ median ratio)." (PMID 24885564, 2014). "Thus, defective mechano-biologic properties observed in DDR2 lacking mice, including altered collagen fiber organization and decreased tumor stiffness, are likely due to defective collagen binding intβ1 activity." (PMID 41492134, 2026). "ID8TB−/− and BPPNM tumor cell lines expressed DDR2, while KPCA did not." (PMID 37996700, 2024). "Thus, in the absence of DDR2 in CAFs, this results in a tumor ECM that is less permissive for metastatic spread." (PMID 37996700, 2024). "DDR2 is a receptor tyrosine kinase (RTK), and it has been shown to be activated through fibrillar collagens and involved in cell behaviors of different types of cancer, including VEGF expression, differentiation, tumor angiogenesis, invasion, and metastatic potential of HNSCC cell lines." (PMID 36849997, 2023). "DDR2 expression in tumor cells did not correlate with POSTN expression." (PMID 35884543, 2022). "In addition, DDRs (DDR1 and DDR2), non-integrin collagen receptors, are expressed on the surface of tumor cell, belonging to the receptor tyrosine kinase (RTK) family." (PMID 34733848, 2021). "Therefore, the number of proliferating tumor cells is increased in liver metastases if DDR2 is not expressed in the liver." (PMID 33917302, 2021). "However, they displayed a slight decrease in phosphorylated DDR2 (at Y740) when compared with +DDR2/−COL1 tumours, which was not statistically significant." (PMID 32047176, 2020). "In CRC, evidence for similar DDR2 tumor-promoting functions is lacking." (PMID 32117772, 2020). "Neither DDR1b nor DDR2 expression altered tumour growth at the primary site." (PMID 32047176, 2020).
tumor (continued). "In summary, analyses of Ddr2-/- FSP1cre tumors, in which the Ddr2 gene was deleted in the majority of CAFs and CD45+ leukocytes, revealed that fewer ECM collagen fibers were present at the tumor-stromal boundary and those present appeared thinner and fragmented." (PMID 31144616, 2019). "Tumor cells that undergo EMT are found to express less epithelial markers such as E-cadherin and cytokeratins but express more mesenchymal markers such as vimentin and N-cadherin, with a possible switch in DDR expression from DDR1 (epithelial) to DDR2 (mesenchymal)." (PMID 27014069, 2016). "Additionally, DDR2 signaling may mediate collagen’s impact on immunotherapy response, as joint administration of anti-PD-1 antibodies and a DDR2 inhibitor boosts CD8+ T-cell infiltration and decreases tumor burden in multiple mouse cancer models." (PMID 40721833, 2025). "Thus, in this model system, +DDR2, but not +DDR1b, tumours show a strong downregulation of KIBRA." (PMID 32047176, 2020). "However, implantation of DDR1b- or DDR2-expressing HT1080 cells with collagen I significantly accelerated tumour growth rate, an effect that could not be observed with collagen I in the absence of DDR induction." (PMID 32047176, 2020). "CTC CNAs, including amplifications of MYC, BCL6, DDR2, SOX2 and deletions of CDKN2A/B, were more likely to be shared with residual rather than primary tumor." (PMID 35087134, 2022). "MST2 was consistently downregulated downstream of both +DDR2/+COLI and +DDR1b/+COLI tumours compared to tumours that do not express DDRs." (PMID 34957097, 2021). "Furthermore, the presence of both DDR2- and POSTN-expressing CAFs resulted in a greater tumor load than the presence of CAFs lacking DDR2 and POSTN." (PMID 38903506, 2024). "Despite of this, we did not observe a very high expression correlation between DDR2 and RET in the R2 tumor datasets (not shown), which could suggest expression in different tumor cell subpopulations." (PMID 34716856, 2022). "Immunoblot analyses of the ±DDR/−COL1 tumours revealed that neither DDR1b nor DDR2 expression altered the levels of either YAP1 and its phosphorylated forms, MST1 and MST2, LATS1 or KIBRA, when compared to tumours with repressed DDRs (+DOX)." (PMID 32047176, 2020). "The tumour growth rate of +DDR1b/+COL1 and +DDR2/+COL1 tumours was significantly faster than that of +DDR tumours without COL1 (p = 0.011 for DDR1b and p = 0.007 for DDR2)." (PMID 32047176, 2020). "Thus, it will be interesting to evaluate the effects of other matrices such as Matrigel, which contains COL4, a ligand for DDR1 but not DDR2, to further address the specificity of DDR-ECM interactions in regulation of tumour growth." (PMID 32047176, 2020). "Interestingly, DDR1b, but not DDR2, completely hindered the ability of HT1080 cells to form lung colonies after intravenous inoculation, suggesting a differential role for DDR1b in primary tumour growth and lung colonization." (PMID 32047176, 2020).